NOD2 (nucleotide binding oligomerization domain containing 2)
Diseases named in the same sentence as NOD2 in open-access papers (continued):
Sharing a sentence is not in itself a finding about the gene and the disease.
Crohn disease (continued). "Polymorphisms of the NOD2 gene are associated with an increased risk of Crohn's disease in humans and Johne's disease in cattle." (PMID 19772668, 2009). "The most significant finding in the IBD research has been identification of mutations in the gene that encodes Nod2 (nucleotide-binding oligomerization domain 2) protein in a subgroup of patients with Crohn's disease." (PMID 19723304, 2009). "Missense mutations in NOD2 cause Blau syndrome and an increased susceptibility to Crohn's disease (MIM 266600)." (PMID 20003547, 2009). "Mutations in domain NBD and LRRs of NOD2 gene are frequently observed in patients with Crohn's disease." (PMID 19723304, 2009). "In regard to genes encoding CARD-containing proteins, mutations in the peptidoglycan receptors NOD1 and NOD2 have been associated to several inflammatory disorders, including Crohn's disease, Blau syndrome and asthma." (PMID 19859543, 2009). "Death was delayed in Nod2 deleted and Crohn's disease associated Nod2 mutated mice orogastrically inoculated with Y. pseudotuberculosis." (PMID 18648508, 2008). "For example, the NOD2 gene, which was the first identified susceptibility gene for Crohn disease, carries three susceptibility variants which account for most of the observed effects." (PMID 18560565, 2008). "NOD2 mutations have been associated with Crohn's Disease (CD), a Human condition characterised by a chronic or relapsing inflammation on the digestive tract." (PMID 18648508, 2008). "CARD15/NOD2 mutations are associated with susceptibility to Crohn's Disease (CD) and Graft Versus Host Disease (GVHD)." (PMID 17565376, 2007). "Caspase Recruitment Domain 15 (CARD15) also known as Nucleotide oligomerisation domain 2 (NOD2) has been associated with Crohn's Disease (CD) and graft versus host disease (GVHD)." (PMID 17565376, 2007). "Truncated NOD2 proteins are encoded by mutations in the NOD2 gene that predispose individuals to Crohn's disease, a granulomatous inflammatory bowel disease." (PMID 17705850, 2007). "Mutations in the leucine-rich repeat region of NOD2, which lead to an impaired recognition of muramyl-dipeptide, have been associated with Crohn disease, a human chronic inflammatory bowel disease." (PMID 18096043, 2007). "Inflammatory bowel disease (IBD) is a typical example as patients with longstanding IBD are at an increased risk for developing colorectal cancer (CRC) and mutations of the NOD2/CARD15 gene increase the risk for Crohn's disease (CD)." (PMID 17389035, 2007). "NOD2 has been linked genetically to increased risk for Crohn's disease, and is a sensor of bacterial peptidoglycans." (PMID 16322770, 2005). "Mutations in the innate immune receptor NOD2 are the greatest single genetic risk factor for Crohn's disease, yet the mechanisms by which NOD2 regulates intestinal homeostasis remain unclear." (PMID 42263101, 2026). "Therefore, any potential influence of Crohn’s disease-associated NOD2 mutations on CCL20 serum levels was ruled out35." (PMID 40542081, 2025). "In NOD2-associated diseases, for instance, the three main variants, NOD2 R702W, G908R, and L1007fs are associated with up to 40% of cases of Crohn disease, and these variants are also shared by Yao syndrome, formerly designated as NOD2-associated autoinflammatory diseases." (PMID 40282361, 2025). "Furthermore, dendritic cells from patients expressing the Crohn disease-associated NOD2 variant exhibited a reduction in lysosomal localization of AIEC bacteria, which was accompanied with diminished autophagy-mediated bacterial killing." (PMID 40910070, 2025). "Variants in NOD2 have been associated with Crohn’s disease and Blau syndrome." (PMID 40428427, 2025). "Since MDP-induced CCL20 expression via the TLR5/NOD2 response loop is known to be influenced by Crohn’s disease-specific NOD2 mutations, we speculated that NOD2 mutations might impact systemic CCL20 levels and explain this specificity." (PMID 40542081, 2025).
Crohn disease (continued). "The results also suggest that targeting ABHD17 isoforms could restore functionality to specific Crohn’s disease-associated NOD2 variants, offering a potential therapeutic strategy." (PMID 40054525, 2025). "Similarly, homozygous carriers of NOD2 loss-of-function mutations exhibit a >40-fold increased risk of developing the autoimmune condition Crohn’s disease." (PMID 38612613, 2024). "In addition, NOD2 harbors two crucial S-palmitoylation sites, and several NOD2 mutant proteins associated with Crohn’s disease exhibit reduced palmitoylation levels." (PMID 39329913, 2024). "Furthermore, it was discovered that the DCs derived from Crohn's disease patients who expressed NOD2 or ATG16L1 risk alleles associated with the disease were impaired in antigen presentation, bacterial transport, and autophagy induction." (PMID 39883213, 2024). "They made the intriguing hypothesis that low DL-endopeptidase abundance in the gut microbiota of some Crohn’s Disease (CD) patients might phenocopy the effect of CD-associated NOD2 polymorphism, due to diminished NOD2 agonist production by the gut microbiota." (PMID 39239828, 2024). "One of them is, rs2066847_G > GC, a NOD2 frameshift mutation, which is reported as a pathogenic variant for inflammatory bowel disease in ClinVar and was associated with several phenotypes related to Crohn’s disease and mouth ulcers in our analysis." (PMID 38997278, 2024). "NOD2 was the first gene implicated in Crohn's disease susceptibility, and mutations in the NOD2 gene may lead to aberrant activation of the immune system, which can increase the likelihood of developing Crohn's disease." (PMID 39883213, 2024). "Furthermore, deficiency of NOD2 in Paneth cells impedes antimicrobial peptide secretion, thereby resulting in a functionally impaired phenotype characteristic of Crohn’s disease-associated mutations in NOD2." (PMID 39329913, 2024). "Moreover, it has been found that ATG16L1 and NOD2 both support the autophagy-dependent antimicrobial pathway, which is modified by Crohn's disease-associated mutations in a way that is specific to certain cell types." (PMID 39883213, 2024). "NOD2 mutations are linked to Crohn’s disease (40% patients), Blau syndrome, and YAOS." (PMID 37928541, 2023). "Vitamin D deficiency may be linked to the genetics of Crohn’s disease, as its pathogenesis is associated with attenuated NOD2 or an antimicrobial peptide function." (PMID 37834314, 2023). "Interestingly, Crohn’s disease-associated mutant forms of NOD2, namely R702W and 3020insC, exhibit diminished protein stability." (PMID 37869013, 2023). "It is believed that intestinal recruitment of monocytes from Crohn’s Disease (CD) patients who carry NOD2 risk alleles may repeatedly give rise to recruitment of pathogenic macrophages." (PMID 37415975, 2023). "NOD2 mutations can cause GI symptoms as in Crohn disease and Yao syndrome." (PMID 38343435, 2023). "Interestingly, the variants in LRRK2 and NOD2 found in the twins had previously been identified as genetic modulators for risk of Parkinson’s and Crohn’s diseases with the two LRRK2 variants showing antagonistic pleiotropy." (PMID 36972292, 2023). "In addition, the aHUS patient carries a frameshift mutation (CADD Score: 35) in the NOD2 gene, known to be positively associated with Crohn’s disease, another autoinflammatory syndrome." (PMID 37477760, 2023). "Variants of the NOD2 gene were initially associated with an increased risk of Crohn`s disease." (PMID 36795715, 2023). "In addition, the polymorphism of NOD2 gene variants in Crohn’s disease led to decreased levels of NF-κB activation and an attenuated response to MDP-stimulation." (PMID 37833958, 2023). "Moreover, the risk of developing Crohn’s disease has been linked to genes which regulate components in the NOD2 signaling pathway, like ATG16L1, CARD9 and RIPK2." (PMID 37833958, 2023). "The polymorphism of NOD2 is linked to Crohn’s disease (CD) pathogenesis." (PMID 36694274, 2023).
Crohn disease (continued). "Mutations in NOD2 are associated with two granulomatous disorders, Blau syndrome and Crohn disease." (PMID 37415984, 2023). "In addition to immunodeficiency, mutations of the NOD2 gene have also been linked with several atopic diseases and autoimmune conditions such as rheumatoid arthritis and Crohn's disease (CD)." (PMID 37288206, 2023). "NOD2 mutations are associated with Crohn’s disease, suggesting that aberrant NOD2-RIP2-XIAP signaling may contribute to inflammatory bowel disease (IBD)." (PMID 37041175, 2023). "Loss-of-function variants in the nucleotide-binding oligomerization domain-containing protein 2 (NOD2) gene are associated with an increased risk of developing Crohn’s disease, a subtype of human chronic IBD, where specific changes in fecal viral communities have also been described." (PMID 36413074, 2023). "NOD2 polymorphisms are strongly associated with Crohn’s disease yet a long-hypothesized role for mycobacteria in Crohn’s disease remains unproven." (PMID 35418999, 2022). "Interestingly, Crohn’s disease susceptibility genes (NOD2,TNSF15) have been shown to be associated with leprosy in a Vietnamese population." (PMID 36146565, 2022). "Finally, the authors provide evidence that several NOD2 polymorphisms associated with Crohn’s disease lead to aberrant S-palmitoylation." (PMID 35159374, 2022). "Polymorphisms in NOD2 are one of the greatest genetic risk factors for Crohn's disease." (PMID 35299671, 2022). "Three different non-synonomous NOD2 polymorphisms, R702 W, G908R, and L1007fsincC, account for ~80% of all NOD2-associated cases of Crohn's disease and they have been reported to cause a loss of receptor function in response to muramyl dipeptide (MDP) stimulation." (PMID 35299671, 2022). "Additionally, the polymorphisms of NOD2 (nucleotide-binding oligomerization domain containing two) were found to be with susceptibility to Crohn’s disease." (PMID 36200036, 2022). "NOD2 deficiency could result in dysregulated immune responses to gut bacteria to contribute to the progression of Crohn’s disease." (PMID 36200036, 2022). "Genetic variations in genes encoding for autophagy-related 16-like 1 (ATG16L1), Unc-51-like autophagy-activating kinase (ULK1), immunity-related GTPase family M protein (IRGM) and nucleotide-binding oligomerization domain-containing protein 2 (NOD2) have all been associated with Crohn's disease." (PMID 33973626, 2021). "Failure to engage MDP–NOD2 signalling could therefore severely compromise the regenerative ability of the intestinal epithelium and perpetuate inflammatory damage, as exemplified in Crohn’s disease, frequently associated with NOD2 mutations or polymorphisms." (PMID 33673710, 2021). "It has been suggested that ASCA positivity may be associated with a specific underlying HS genotype as this antibody has been associated with Crohn’s disease patients harbouring specific NOD2 variants." (PMID 34696185, 2021). "The human NOD2 protein is a cytoplasmic receptor for bacterial molecules principally expressed in Paneth cells and it was identified as a susceptibility gene for Crohn’s disease." (PMID 34195099, 2021). "Granulomas in Blau syndrome and granulomas in NOD2-associated Crohn’s disease show distinct morphologic features with granulomas with large lymphocytic coronas, emperipolesis of lymphocytes within multinucleated giant cells and giant cell apoptosis seen only in Blau syndrome." (PMID 34201078, 2021). "Interestingly, the variant in PTPN22 is associated with reduced risk of Crohn’s disease while loss-of-function mutations in NOD2 are associated with increased risk of Crohn’s disease." (PMID 33717184, 2021). "Moreover, human α-defensin expression is reduced in Crohn’s disease patients, particularly in those with NOD2 mutations." (PMID 34195099, 2021).
Crohn disease (continued). "Collectively, these analyses show substantially larger effects for NOD2 homozygotes and compound heterozygotes than heterozygotes only and indicate that the genetic contribution of NOD2 alleles, in a subset of Crohn’s disease patients, is consistent with a recessive disease model." (PMID 33692434, 2021). "Both NOD2 and PLCƔ2 mutations are associated with Crohn’s disease." (PMID 34201078, 2021). "While our observations strongly support recessive inheritance of NOD2 variants as a driver of early onset Crohn’s disease, we observed incomplete penetrance, as evidenced by homozygous or compound heterozygous NOD2 variant carriers that do not have a clinical presentation of IBD65–67." (PMID 33692434, 2021). "Little experiences reported that patients carrying NOD2/CARD15 polymorphisms could develop a more aggressive form of Crohn's disease showing a trend for an early surgery followed by multiple surgical interventions." (PMID 33708009, 2021). "Importantly, NOD2 polymorphisms/mutations are a key pathogenic event in Crohn’s disease, as NOD2 deficiency leads to exacerbated gut inflammation due to impaired bacterial clearance." (PMID 34956195, 2021). "miRNAs have been shown to regulate specific genes associated with Crohn’s disease (CD) including nucleotide-binding oligomerization domain-containing protein 2 (NOD2), IL-6, and tumor necrosis factor (TNF), but further studies are needed to clarify their precise role and their use in IBD management." (PMID 33138015, 2020). "Yet, despite that Paneth cells are the predominant cell types expressing NOD2 at the intestinal mucosa, it is unclear whether mutations in NOD2 are indeed causing the altered expression of the human defensins in ileal Crohn's disease." (PMID 32655555, 2020). "In addition, NOD2 mutation leads to a decrease in α-defensin production in Paneth cells in patients with Crohn’s disease and amounts of α-defensin peptides decrease in obesity." (PMID 33154750, 2020). "NOD2 variants are the strongest genetic predictors for susceptibility to Crohn’s disease (CD)." (PMID 32716958, 2020). "Minor allele frequencies (MAF) of the three main NOD2 SNPs rs2066844 (p.Arg702Trp), rs2066845 (p.Gly908Arg), and rs2066847 (p.Leu1007fsX1008) for each genotype (homozygous, heterozygous and compound heterozygous) in patients with Crohn’s disease." (PMID 32716958, 2020). "This might be highly relevant to the pathogenesis of chronic inflammatory disorders such as Crohn’s disease, in which loss of function associated polymorphisms in the NOD2 gene are associated with increased susceptibility to disease." (PMID 29198621, 2019). "Moreover, it was shown that MDP can upregulate PD-L1 in healthy monocytes, but in patients with Crohn's disease, carrying the Leu1007 frameshift mutation of the NOD2 gene, such effect was completely lost." (PMID 31447834, 2019). "NOD2 expression on DCs may also play a critical role in their responses to microbes, because DCs derived from NOD-2 deficient Crohn's disease patients have an impaired ability to induce IL-17 production upon MDP challenge." (PMID 31886308, 2019). "Additionally, nucleotide-binding oligomerization domain-containing protein 2 (NOD2) mutation leads to a decrease in α-defensin production in Paneth cells in patients with Crohn’s disease and the amount of immunoreactive α-defensin decreases in obese people." (PMID 31752111, 2019). "NOD2 remains the most strongly associated Crohn's disease susceptibility gene." (PMID 31114588, 2019). "Finally, we examined DCs from patients with Crohn's disease expressing associated NOD2 variants and found they were unable to induce cross-presentation following NOD2 and TLR2 triggering." (PMID 31114588, 2019). "Furthermore, in conjunction with these two studies, the consensus among researchers places NOD2 heterozygote alterations with a doubled risk for Crohn’s disease, as well as around 20 times the risk for Crohn’s disease in NOD2 homozygotes." (PMID 31723489, 2019).
Crohn disease (continued). "Previous work from our group demonstrated that vimentin interacts with the pattern recognition receptor (PRR) nucleotide-binding oligomerisation domain-containing protein 2 (NOD2), a bacterial sensor protein that is strongly associated with inflammatory bowel disease Crohn’s disease (CD)." (PMID 30699149, 2019). "Moreover, the G908R SNP (Gly908Arg) is one of the most common SNPs in NOD2 that is associated with Crohn’s disease." (PMID 30200338, 2018). "However, we show the feasibility of using gene burden tests for Crohn’s disease sequencing studies by demonstrating that VAAST has the ability to uncover statistical association in NOD2 among 63 genes and only 205 cases." (PMID 30166421, 2018). "Early GWASs showed that with the exception of NOD2, the typical effect size of Crohn's disease susceptibility locus was modest (odds ratio < 1.3).38, 39 Herein, we reported for the first time a new Crohn's disease susceptibility SNP with a high odds ratio in the Chinese population." (PMID 29441677, 2018). "It is unclear as to whether repair of NOD2 signaling defects might represent a therapeutic strategy for patients expressing Crohn’s disease-associated polymorphisms." (PMID 29515999, 2018). "All these findings prompted us to examine whether NOD2 could interact with other genes to influence Crohn's disease risk in the Chinese cohort." (PMID 29441677, 2018). "Furthermore, studies focusing on the genetic background of Crohn's disease(CD) have highlighted its susceptibility in patients carrying several NOD2 polymorphisms." (PMID 29881342, 2018). "Also, signaling of the NLR family member NOD2 induces IL-10 expression, and NOD2 mutations are associated with Crohn’s disease." (PMID 29124320, 2018). "Crohn’s disease is also caused by mutations in the gene encoding NOD2 but the mechanisms behind Crohn’s disease development in XIAP and NOD2 deficient-patients are still unknown." (PMID 29743550, 2018). "This may be highly relevant in the context of chronic intestinal inflammation in which loss of function associated polymorphisms in the NOD2 gene are associated with increased susceptibility to Crohn’s disease." (PMID 29515999, 2018). "In human, the deficiency of NOD2 would cause Crohn’s disease and in grass carp, NOD1 and NOD2 could be upregulated by different immunostimulants." (PMID 30119658, 2018). "Importantly, DCs expressing the Crohn’s disease NOD2 and ATG16L1 variants have reduced autophagic response and MHC class II antigen presentation in response to MDP." (PMID 29515999, 2018). "Additionally, patients with Crohn’s disease with NOD2 polymorphisms have reduced numbers of intestinal LP Tregs due to the role of NOD2 signaling in promoting survival of human regulatory T cells." (PMID 27908847, 2017). "Also, NOD2 appears as a key player in autophagy, including its genetic association with Crohn’s disease." (PMID 28715406, 2017). "While Crohn’s disease patients with NOD2 mutations on average showed a reduced muramyl dipeptide response, the cohort exhibited large individual variance: a small subset had inflammatory responses almost comparable to wild-type patients on both gene and miR-155 regulatory levels." (PMID 29263823, 2017). "NOD2 is implicated in changes in the composition of the intestinal microbiota in Crohn’s disease, but its role on skin microbiota is unknown." (PMID 28647345, 2017). "Mutations in the NOD2 gene associated with Crohn’s disease have also been associated with an increased risk for the development of different types of cancer (Helicobacter pylori-induced MALT lymphoma, colonic adenocarcinoma, and breast and lung cancer) in Caucasians." (PMID 29165176, 2017). "In addition to leprosy, human variants of NOD2 have been associated with susceptibility to Crohn's disease." (PMID 27297389, 2016).